LDHA (lactate dehydrogenase A)
Diseases named in the same sentence as LDHA in open-access papers (continued):
Sharing a sentence is not in itself a finding about the gene and the disease.
breast cancer (continued). "In addition, inhibition of LDHA results in increased glycolysis in MDA-MB-231 breast cancer cells." (PMID 39289349, 2024). "Furthermore, blocking the conversion of lactate to pyruvate for energy production, for example, by inhibiting the enzyme lactate dehydrogenase A (LDHA), increases mitochondrial respiration in breast cancer cells, demonstrating that oxidative metabolism is still functional." (PMID 39123496, 2024). "Notably, increased expression of LDHA served as a vicious positive feedback to reduce tumor cell stiffness and adhesion, which eventually resulted in the proliferation, invasion, and metastasis of breast cancer." (PMID 38905316, 2024). "Similarly, lncRNA SNHG5 directly targetsmiR-299 repression, upregulates BTB domain and CNC homology 1 (BACH1) transcription factor levels, and increases HK2 and PFK1, and lncRNA SNHG7 directly targets miR34a-5p to upregulate LDHA and promote glycolysis in breast cancer." (PMID 37204526, 2023). "In addition, circRNAs can regulate LDHA expression in breast cancer cells." (PMID 37204526, 2023). "Thus, LDHA is a great target for controlling TAM resistance in breast cancer." (PMID 36059650, 2022). "Therefore, LDHA-203, upregulated in AI-resistant breast cancer cells, could increase the lactate production during the glycolytic processes." (PMID 36418319, 2022). "Finally, when LDHA was genetically downregulated or paclitaxel was combined with oxamate, synergistic effects on inducing apoptosis were evidenced in paclitaxel-resistant breast cancer cells." (PMID 35328602, 2022). "However, the proportion of ALDH+ cells (epithelial-like BCSCs, E-BCSCs) was increased and the proportion of CD44+ CD24− cells (mesenchyme-like BCSCs, M-BCSCs) was decreased after LDHA silencing, suggesting a regulatory role of LDHA in E-BCSCs/M-BCSCs transformation in mouse breast cancer cells." (PMID 34178639, 2021). "Once we demonstrated that POU1F1 regulates LDHA and that pharmacological or genetic manipulation of LDHA induces phenotypic changes in breast cancer cells that modify cancer progression, we studied whether POU1F1 could have an impact on TME, specifically on fibroblasts." (PMID 33714987, 2021). "In light of the cell-specific protein localization of LDHB in adipocytes and LDHA in cancer cells, which was particularly prominent at the invasive front of the tumor, it is worth considering lactate oxidation by adipose tissue as part of the metabolic coupling in premenopausal breast cancer." (PMID 33353120, 2020). "In hypoxic breast cancer cells, oxidative stress-induced overexpression of miR-181c blocked HIF-1α accumulation and diminished hypoxia-inducible levels of glycolysis enzymes, including glycolysis-associated glucose transporter-1 (GLUT1), hexokinase 2 (HK2), PDK1, and lactate dehydrogenase A (LDHA)." (PMID 35006436, 2020). "Thus, simultaneous targeting PDL1 and LDHA, combined with immunotherapy and metabolically targeted treatments, might represent a new breast cancer treatment, especially in TNBC." (PMID 30781524, 2019). "In addition, co-expression of PDL1 and LDHA indicated a poor outcome in breast cancer." (PMID 28915924, 2017). "Moreover, we found that miR-34a targets LDHA to regulate metabolism in breast cancer." (PMID 29037220, 2017). "We then evaluated whether 14-3-3ζ and LDHA levels hold prognostic values for breast cancer." (PMID 27150057, 2016). "Targeting LDHA through miR-34a could be a potential therapeutic strategy in breast cancer." (PMID 26902416, 2016). "In breast cancer cells, KCNK1 interacts with LDHA activation, enhancing glycolysis and lactate synthesis." (PMID 41190507, 2025). "In breast cancer, lncRNA DIO3OS (DIO3 Opposite Strand Upstream RNA) contributes to aromatase inhibitor resistance by enhancing the stability and expression of LDHA mRNA through PTBP1." (PMID 40264038, 2025).
breast cancer (continued). "Basal-like breast cancer typically demonstrates a Warburg-like phenotype, characterized by elevated GLUT1, MCT4, and LDHA expression, which increases glucose uptake and lactate secretion." (PMID 40630197, 2025). "In breast cancer, NAT10-mediated stabilization of JunB mRNA upregulates LDHA expression, creating an immunosuppressive niche via lactate-driven inhibition of cytotoxic T cells." (PMID 40588654, 2025). "Galloflavin, a derivative of gallic acid, is a significant antiglycolytic drug that inhibits both LDHA and LDHB in TNBC and estrogen receptor-positive/progesterone receptor-positive (ER +/PR +) breast cancer." (PMID 40295451, 2025). "The lncRNA DIO3OS stabilizes the mRNA of lactate dehydrogenase A (LDHA) by protecting the integrity of its 3′UTR and activates glycolytic metabolism in aromatase inhibitor resistant breast cancer cells." (PMID 40919131, 2025). "In parallel, LDHA inhibitors such as FX11 and galloflavin have demonstrated efficacy in preclinical models of lymphoma, pancreatic, and breast cancers by reducing lactate production, disrupting glycolysis, and inducing oxidative stress." (PMID 40710349, 2025). "In breast cancer, KCNK1 upregulates LDHA activity and promotes H3K18la enrichment, which in turn increases LDHA gene expression and downstream oncogenes, forming a KCNK1–LDHA–H3K18la–LDHA positive feedback loop that drives metastasis and chemoresistance." (PMID 40843350, 2025). "For example, FOXD1 enhances the aerobic glycolysis process by increasing HK2, LDHA, and GLUT1 expression in breast cancer cells." (PMID 41214670, 2025). "Alternatively, it was recently reported that TG2 deletion in breast cancer cells reduced LDHA expression, and TG2 overexpression increased LDHA expression, via the MEK/ERK pathway." (PMID 38959068, 2024). "One of the key enzymes in glycolysis is lactate dehydrogenase A (LDHA) which converts pyruvate to lactate and has been reported to be involved in paclitaxel resistance in breast cancer." (PMID 38413011, 2024). "In particular, we focused on the modulation of the expression and activity of PKM2 and the expression of LDHA in the glycolysis pathway, as well as, on the expression of miR-let-7a in MCF-7 and MDA-MB-231 breast cancer cell lines." (PMID 38773429, 2024). "KCNK1 expression was positively correlated with that of LDHA, Pan Kla, ZWINT, ECT2, ANLN, and EZR, reconfirming that KCNK1 played an important role in the proliferation and metastasis of breast cancer." (PMID 38905316, 2024). "The long noncoding RNA (lncRNA) DIO3OS preserves the integrity of the LDHA 3’ untranslated region (3’UTR) and upregulates LDHA expression through its interaction with PTBP1, thereby stimulating glycolysis in drug-resistant breast cancer cells." (PMID 39403606, 2024). "Another report on breast cancer indicated that the promoters of the rate-limiting glycolytic genes FBP1, PKM and LDHA were specifically methylated in CAFs, where PKM and LDHA expression levels increased, thereby increasing glycolysis in CAFs." (PMID 39408814, 2024). "More importantly, glycolysis enzymes (GPI, LDHA, TPI1, and ALDOA) were significantly enriched in the exosomes of primary tumors of both canine mammary tumor and human colorectal tumor, compared to metastases." (PMID 38419074, 2024). "MiR-30a-5p is a key regulatory molecule in breast tumors, and it inhibited breast cancer cell migration, invasion, and glycolysis by targeting MTDH (3′-untranslated region of metadherin) and LDHA (Lactate dehydrogenase A)." (PMID 39239646, 2024). "The results showed that the number of pseudopodia in breast cancer cells was lower after knocking down KCNK1, while the number of pseudopodia in cells increased after overexpressing LDHA." (PMID 38905316, 2024). "High expression of isoenzymes such as lactate dehydrogenase-A (LDHA) and lactate dehydrogenase-B (LDGB) in TNBC confirms the dependence of cells in this subtype of breast cancer on anaerobic glycolysis and correlates with a poor prognosis." (PMID 39852119, 2024).
breast cancer (continued). "ChIP-qPCR also showed that overexpression of LDHA blocked the inhibitory effect of KCNK1 knockdown on H3K18la and p300 binding of ZWINT, ECT2, ANLN, EZR, and LDHA in breast cancer cells." (PMID 38905316, 2024). "Several known proteins (including HSP90AB1, HSPB1, LDHA, ENO1, PGK1, KRT18, and AKR1C2) and pathways were observed between model breast cancer cell lines related to hormone response, cell metabolism, and cell morphology." (PMID 36937585, 2023). "Recently, lactate dehydrogenase-A (LDH-A) has been found to protect the dryness of cancer and recruit tumor-related macrophages to promote breast cancer progression." (PMID 36875841, 2023). "Subsequent work revealed that in ErbB2-amplified human breast cancer cells, ErbB2 activates HSF1, which in turn binds to the LDHA gene promoter to induce LDHA expression and promote glycolysis and growth." (PMID 37444501, 2023). "In breast cancer, quercetin down-regulates Akt, induces autophagy, and suppresses glucose uptake protein levels of PKM2, GLUT1, LDHA, MMP2, MMP9, and VEGF." (PMID 38001865, 2023). "BA hampered the intensity of glycolysis, glucose uptake, and lactate production and suppressed c-Myc, LDHA, and PDK1 in breast cancer cells." (PMID 38001865, 2023). "CircKLHL24 can inhibit the proliferation and migration of breast cancer cells, downregulate the levels of HK2, GLUT1 and LDHA, and upregulate the expression of ALX4 by competitively binding miR-1204, thereby achieving tumor inhibition." (PMID 37204526, 2023). "Here, we demonstrate that lncRNA DIO3OS directly interacts with PTBP1 protein in the nucleus and further stabilizes the mRNA of LDHA by protecting the integrity of its 3’UTR, ultimately activates glycolytic metabolism in AI-resistant breast cancer cells." (PMID 36418319, 2022). "In conclusion, miR-361-5p inhibits glycolysis in breast cancer cells and FGFR1, a miR-361-5p target, reverts the anti-glycolytic function of those small RNAs and represses OXPHOS by upregulating LDHA and pyruvate dehydrogenase kinase-1 (PDHK1) function." (PMID 35348905, 2022). "It was demonstrated that elevated lactate production through induced LDHA activity directs USP28-mediated deubiquitination and the stabilization of MYC, thereby promoting stem-like traits in breast cancer." (PMID 36230479, 2022). "Thus, LDHA may serve as a therapeutic target for breast cancer resistance." (PMID 36059650, 2022). "Data presenting the role of LDHA in drug resistance described that in chondrosarcoma inhibiting LDHA increased cancer cell sensitivity to DOX, in breast cancer cells, led to re-sensitization to paclitaxel." (PMID 35433453, 2022). "LDHA inhibitor reversed EMT-like phenomena while reducing the invasion and migration of tamoxifen-resistant breast cancer cells, thus confirming the function of LDHA in EMT regulation." (PMID 35936690, 2022). "Expression of glycolysis-related proteins, like HK2, LDHA, and PKM2, increases in breast cancer cells." (PMID 36188552, 2022). "Screen of the glycolytic metabolites affected by DIO3OS and PTBP1 and further verification of the splicing events in glycolytic enzymes identified LDHA as a key downstream target of DIO3OS and PTBP1 in AI-resistant breast cancer cells." (PMID 36418319, 2022). "Three (LDHA, DBF4B, and MASP1) were predicted to be targeted by miRNA identified as differentially expressed in breast cancer tissues of cases compared to controls in the study of Du and collaborators or Ohzawa and collaborators." (PMID 36627894, 2022). "When combined with LDHA, oxamate can inhibit the conversion of pyruvate to lactate by inhibiting LDH and inhibiting the proliferation and migration of prostate and breast cancer, and its sensitivity can be effectively improved when combined with temozolomide." (PMID 36230492, 2022). "TNBC cells exhibit higher LDHA and AMPK levels and lower oxygen consumption rates than luminal breast cancer cells." (PMID 36109724, 2022).
breast cancer (continued). "Through proteomic profiling, we discovered a metabolic signature comprised of TALDO1, GPI, LDHA, SHMT2, and ADK proteins that were downregulated in Trop2-depleted breast cancer tumors." (PMID 34711841, 2021). "In summary, our data suggest that either blocking LDHA enzymatic activity or decreasing LDHA expression in MCF7-POU1F1 cells reduces proliferation, migration, and invasion of breast cancer cells." (PMID 33714987, 2021). "In the present study, we have utilized these cell lines and shown that the acquired ER −ve cells as well as normal MCF10A express both LDHA and LDHB whereas expression of LDHB is lost in ER +ve breast cancer cells." (PMID 34744727, 2021). "Both POU1F1/LDHA and POU1F1/α-SMA expression correlate with clinical outcome, suggesting POU1F1 as a prognostic factor in breast cancer." (PMID 33714987, 2021). "The study demonstrated that miR-7641 decreased breast cancer cell glycolysis by HK2, GLUT1, LDHA which regulated by HIF-1α." (PMID 34238918, 2021). "As one of the oncogenic transcriptional factors regulating the glycolytic phenotype of breast cancer, c-myc can drive glycolytic programming by directly up-regulating the transcription of glycolysis-related genes including GLUTs, HK2, and LDHA." (PMID 35096814, 2021). "Cardamonin impedes the growth of breast cancer, along with a decrease in HIF-1α and its target genes, such as lactate dehydrogenase A (LDHA), in vivo." (PMID 34575983, 2021). "For example, stress-induced epinephrine secretion activated lactate dehydrogenase A (LDHA) to promote the myc-slug signaling, thereby enhancing the development of breast cancer stem-like traits." (PMID 34689156, 2021). "Moderate intra-tumoral and characteristic inter-tumoral heterogeneity for LDHA and GLS were observed in the studied breast cancers." (PMID 32899149, 2020). "MiR-34a has also been shown to directly suppress lactate dehydrogenase A (LDHA) in colorectal cancer and breast cancer as well as PDL1, an important immune checkpoint inhibitor, in lung cancer and acute myeloid leukemia." (PMID 30781524, 2019). "Using a drug screen that targeted LDHA, we found that a chronic stress–induced cancer stem-like phenotype could be reversed by vitamin C. These findings demonstrated the critical importance of psychological factors in promoting stem-like properties in breast cancer cells." (PMID 30688660, 2019). "In our study, vitamin C suppressed stress-induced LDHA, thus altering the lactate production to inhibit the USP28/MYC/SLUG axis in breast cancer stem cells." (PMID 30688660, 2019). "Subsequently, the effect of PSTMB on LDHA activity in several cancer cells lines, such as human colon cancer HT29, human lung cancer NCI-H1299, human breast cancer MCF-7, human hepatocellular carcinoma Hep3B, and murine lung cancer LLC cells, was examined." (PMID 30850682, 2019). "In breast cancer cells, we found that miR-34a regulated LDHA levels by targeting the 3′ UTR of LDHA." (PMID 26902416, 2016). "Here, we demonstrated that 14-3-3ζ overexpression upregulates LDHA expression and increases glycolysis through the MEK/ERK/CREB signaling axis in early breast cancer, delineating the important signaling pathway for an essential cellular phenotype." (PMID 27150057, 2016). "The ectopic expression of miR-33b downregulated the expression of ADAM9, HMGA2, LDHA, SALL4, SNAI2 and Twist1 by more than 30% but had minimal effects on HIF-1α, RAC1, Yes1 and ZEB1 in these two breast cancer cell lines." (PMID 25919570, 2015). "For instances, the extract from Spatholobus suberectus was shown to inhibit the activity of lactate dehydrogenase A (LDHA), thereby suppressing the aerobic glycolysis in breast cancer cells." (PMID 24626155, 2014). "Oxamate, another LDHA inhibitor, has been investigated in the TNBC and ER +/PR + breast cancer." (PMID 40295451, 2025).
breast cancer (continued). "Our study demonstrates that DATS disrupts glycolytic metabolism in breast cancer cells, as evidenced by a significant reduction in glucose uptake, downregulation of key glycolytic regulators (GLUT1, LDHA, and HIF1α), and diminished lactate production following combination treatment with DOX." (PMID 40861817, 2025). "In a separate investigation, it was demonstrated that betulinic acid inhibits pulmonary metastasis in breast cancer by upregulating glucose-regulated protein 78 (GRP78) and downregulating lactate dehydrogenase A (LDHA) and pyruvate dehydrogenase kinase 1 to inhibit lactate production." (PMID 40417000, 2025). "Collectively, elevated levels of LDHA and LDHB in breast cancer tissue could be developed into tissue-based assays." (PMID 41154605, 2025). "Aberrant LDHA and LDHB expression due to hypomethylation of the promoter and the resulting increased lactate concentration are involved in acquired TAM resistance in breast cancer cells." (PMID 40612109, 2025). "To investigate whether KCNK1 affects the invasion and migration of breast cancer cells through LDHA, we knocked down KCNK1 in breast cancer cells while overexpressing LDHA." (PMID 38905316, 2024). "For instance, inhibition of LDHA leads to an increased intracellular pyruvate and NADH level, which drives extracellular matrix (ECM) remodeling and ultimately strengthens collagen protein durability and promotes the progression of breast cancer." (PMID 39678492, 2024). "Knockdown of MIR210HG also downregulated the expression of proteins, such as GLUT1, PKM2, and LDHA, and the discovery of the HIF-1α/MIR210HG axis may also provide a direction for the treatment of breast cancer." (PMID 37204526, 2023). "It has been found that the high expression of PGM5 in Human breast cancer cell lines MCF7 and ZR75-1 can inhibit LDHA and slow down cancer progression, but miR-1224-3p can directly inhibit PGM5, which leads to the proliferation and metastasis of breast cancer cells." (PMID 37204526, 2023). "Moreover, quercetin (30 μM) suppressed glycolysis in the MCF-7 and MDA-MB-231 breast cancer cells, as evidenced by decreased glucose uptake and lactate production with a concomitant decrease in the levels of the GLUT1, PKM2, and LDHA proteins." (PMID 36611972, 2023). "Mechanistically, epinephrine activates LDHA to produce lactate, and the pH adjustment promotes USP28-dependent deubiquitination and stabilization of MYC, which in turn activates genes (such as SLUG) involved in breast cancer stem-like properties." (PMID 37444501, 2023). "We observed that LDHA and MCT1 are upregulated in Taxol-resistant breast cancer cells." (PMID 36059650, 2022). "LDHA overexpression has been reported in lung adenocarcinoma, CAIX in breast cancer and oral squamous cell carcinoma, MCT4 in bladder and breast cancer, and BSG in acute myeloid leukemia." (PMID 36678382, 2022). "Importantly, we demonstrated concomitantly high expression of Zeb1, LDHA, and MCT4 in breast cancer patients with an advanced TNM stage, highlighting that Zeb1-mediated dysregulation of aerobic glycolysis is functionally linked to breast tumor malignancy." (PMID 35246504, 2022). "Overexpression of canonical transcript LDHA-203, but not the unstable transcript LDHA-220, markedly enhances lactate production and promotes breast cancer cell growth." (PMID 36418319, 2022). "Collectively, lncRNA DIO3OS directly interacts with PTBP1 protein in the nucleus and stabilizes the mRNA of LDHA by protecting the integrity of its 3’UTR, which consequently upregulates LDHA expression and activates glycolytic metabolism in AI-resistant breast cancer cells." (PMID 36418319, 2022). "It was demonstrated that knocking-down HIF-2α in MDA-MB-231 breast cancer cells significantly decreased the expression of glycolysis-related gene products, such as HK2, LDHA, SLC2A1 and PDK1, consisting with the suppression of mRNA levels of glycolysis- and hypoxia-related genes." (PMID 35096814, 2021).